XCL1 (X-C motif chemokine ligand 1)
Diseases named in the same sentence as XCL1 in open-access papers (continued):
Sharing a sentence is not in itself a finding about the gene and the disease.
tumor (continued). "NK cells produce chemoattractants, such as CCL5 and XCL1, that recruit cDC1s to tumor sites, meanwhile, tumor-derived factors, such as PGE2, can suppress NK cell viability and chemokine production." (PMID 40165899, 2025). "In future work, the system study of function of XCL1 in anti-tumor immunity would improve the outcomes of tumor patients." (PMID 41426973, 2025). "Given the key role of XLC1 in tumor immunity microenvironment, the XCL1 becomes an important factor to regulate anti-tumor immunity." (PMID 41426973, 2025). "In contrast, patients with viral-related HCC have an improved prognosis when their CD8+ T cells are activated and produce chemokine X-C motif chemokine ligand 1 (XCL1), which enhances the tumor-attacking immune response by activating other immune cells." (PMID 40869156, 2025). "Alginate formed an in situ gel at the physiological Ca2+ concentration in tumors, and the release of XCL‐1 chemokines attracted XCR‐1+ DCs into tumors, promoting cross‐presentation of tumor‐associated antigens by the tumor‐infiltrated DCs." (PMID 41287898, 2025). "Tumor‐derived PGE2 can impair NK cell function by negatively affecting the release of XCL1 and CCL5 and the expression of their receptors on cDC1." (PMID 39973474, 2025). "Identically, Xcl1 mRNA and XCL1 protein levels were increased markedly in these tumors using qPCR, as well as tumors from MC38 tumor-bearing Bcl9/Bcl9l deficiency mice." (PMID 38811552, 2024). "Our finding of tumour cells overexpressing NK cell markers XCL1/2 and CD160 correlating with the lowest level of immune cell infiltration suggests a tumour-intrinsic immune evasion mechanism of ESCC." (PMID 39419971, 2024). "The immunogenic role of XCL1 and its underlying functional mechanisms in the development of ESCC and other tumours need further investigation." (PMID 39419971, 2024). "Tumor growth was monitored; the results showed that tumor growth was inhibited to some extent by both MS and XCL1-MS vaccines compared with the vector, and the inhibitory effect of XCL1-MS was significantly stronger." (PMID 38339158, 2024). "IL‐15 has been used clinically in tumor therapy, where it recruits CD8+ T cells and NK cells to the tumor site, leading to the secretion of XCL1 and the subsequent attraction of dendritic cells expressing XCR1 receptors." (PMID 38887195, 2024). "NK cells can also drive tumor inflammation by producing chemokines (XCL1 or XCL2) or cytokines (e.g., IFN-γ) and recruiting and maturing other immune cells to form the tumor microenvironment." (PMID 39668817, 2024). "XCL1 is a chemokine mainly produced by activated TC or NK cells and has been correlated to PD-L1 expression on tumor cells." (PMID 39001353, 2024). "We also observed a positive correlation between XCL1/2 gene expression and tumour cellularity based on sequencing data." (PMID 39419971, 2024). "XCL1 or CD160 expression co-localised with LGR6 expression, and co-expression within tumours was seen in 16.3% (16/98) of our cohort for XCL1 and LGR6, and 27.8% (25/90) for CD160 and LGR6." (PMID 39419971, 2024). "Research has shown that NKs can produce chemokines CCL5 and XCL1 to recruit cDC1 into the tumor microenvironment, which is necessary for tumor immune control, and the disruption of this process can lead to cancer immune escape." (PMID 38339158, 2024). "These interesting data exposed the function of NK cells in enrolling dendritic cells into the tumor microenvironment by releasing the XCL1 chemokine." (PMID 36980182, 2023). "On the other hand, XCL1 is more specific for cDC1 attraction, while both cDC1 and cDC2 have been shown to be relevant for anti-tumor immunity." (PMID 37622122, 2023). "Among the genes encoding secreted proteins, the c-Kit+ ILC2_c1 population expressed XCL1 that involved in the recruitment of dendritic cells, and fibrosis-associated gene TGFB1 with either tumor-suppressing or tumor-promoting effects." (PMID 36960063, 2023).
tumor (continued). "XCL1 expression was also correlated with trends of reduced tumor size in the combination group (p = 0.0591, R2 = 0.321)." (PMID 36741387, 2022). "NK cells communicate with cDC1 by expressing Xcl1, which leads to the chemotaxis of cDC1 into the tumor, and CD39i can enhance this effect by increasing NK cells in the tumor." (PMID 36347860, 2022). "XCL1 is mostly secreted by tumor-resident CD56low NK cells, CCL4 and CCL5 are primarily generated by CD56low and CD56high NK cells, and CD8+ T cells are all part of this profile." (PMID 36703982, 2022). "Further, we prove that similar vector designs can be applied in PAX3-FOXO1-driven ARMS, and to express immunomodulatory cytokines, such as IL-15 and XCL1, in tumor entities typically considered to be immunologically ‘cold’." (PMID 36229873, 2022). "In both models, tumoral overexpression of CCL3, CCL19, CCL21, and XCL1 significantly repressed tumor growth, despite the differential overexpression levels in these cell lines." (PMID 36654820, 2022). "To demonstrate the applicability of the platform, we generated XCL1(CC3)-antigen constructs using distinct tumor epitopes." (PMID 35428705, 2022). "In particular, the ratio of ZsGreen+ cDCs was upregulated in XCL1-overexpressing tumors, suggesting an enhanced uptake of tumor antigens." (PMID 36654820, 2022). "Fusion of an Ag and XCL1 to create an XCL1-based vaccibody turned a poorly immunogenic tumor microenvironment into a highly immunogenic one." (PMID 35806328, 2022). "In a murine melanoma model, NK cells secreted the chemokines CCL5 and XCL1, recruiting cDC1 dendritic cells into the tumor microenvironment, leading to controlled tumor growth." (PMID 35203609, 2022). "Higher percentages of ZsGreen+ cDCs were found in the lymph nodes of CCL3- and XCL1-overexpressing tumor models." (PMID 36654820, 2022). "In mouse CRC models, we demonstrated that all four chemokines, including CCL3, CCL19, CCL21, and XCL1, effectively inhibited tumor growth." (PMID 36654820, 2022). "Early activated (pro-memory) CD8+ T cells expressed marker genes IL7R (cluster 5 in Paratumor) or XCL1 (cluster 1 in Tumor) while with low expression of activated makers such as HLA-DR." (PMID 33429363, 2021). "Many of these tumor-infiltrating T cells highly expressed chemotactic genes, such as CCL5 and XCL1, that can attract additional T cells and professional antigen presenting cells (e.g., dendritic cells) into the tumor microenvironment." (PMID 34836966, 2021). "To confirm the protein-level expression and localization of XCL1 in tumor tissue, we added immunohistochemistry for 24 MCT-SCC/ASC and 19 HGSC samples." (PMID 32115573, 2020). "Intriguingly, 11 of 13 (85%) XCL1-positive MCT-SCC/ASCs showed a high tumor infiltration rate of CD8-positive T cells and PD-L1 expression on tumor cells." (PMID 32115573, 2020). "In mice, administration of XCL1 linked with antigen (e.g., OVA) targeting cDC1s results in an antigen-specific T cell response and reduced tumor growth." (PMID 33679726, 2020). "Although blood and tumor-infiltrating NK cells express predominantly perforin and granzyme genes that are related to cytotoxicity, tumor-infiltrating NK cells upregulate XCL1, XCL2, CCL3, CCL4, CCL4L2, and CCL5 that are chemokine genes." (PMID 33424862, 2020). "Other approaches have been assessed in a few clinical trials, such as increasing the expression of XCL1 within the tumor in order to recruit CD141+ XCR1+ DCs." (PMID 32075343, 2020). "In mice, the targeting of tumor antigens to cDC1, using XCL1 or mAbs as vectors, proved to elicit a potent CTL response, preventing the outgrowth of inoculated tumors without relevant adverse effects." (PMID 32075343, 2020). "These cells play an active role in anti-tumor effects partly by secreting XCL1 and recruiting cDC1 cells for tumor antigens presenting, which will, in turn, attract more CD8+ T cells to exert cytotoxic response." (PMID 33298893, 2020).
tumor (continued). "In a mouse BRAFV600E-mutant melanoma model, intratumoral NK cells upregulate Xcl1 and Ccl5 whereas NK cell depletion lowered the numbers of tumor-infiltrating cDC1." (PMID 33424862, 2020). "Tumor-infiltrating NK cells differentiate into two main populations with distinct profiles of chemokine gene expression: XCL1+XCL2+ NK cells and CCL3+CCL4+CCL4L2+CCL5+ NK cells." (PMID 33424862, 2020). "Gene expression analysis of the whole tumor revealed a ~4 x increase in the expression of XCL1 mRNA on hetIL-15 administration." (PMID 32461349, 2020). "Analysis of XCL1 protein within the tumor was performed by ELISA at 6 hours after hetIL-15 IP administration." (PMID 32461349, 2020). "This profile includes XCL1, mainly secreted by tumor resident CD56low NK cells, and CCL4 and CCL5 mostly produced by CD56low and CD56high NK cells and CD8+ T cells." (PMID 33679726, 2020). "hetIL-15 upregulated intratumoral Xcl1 mRNA expression, and tumor lysates from hetIL-15 treated mice were enriched in XCL1 chemokine." (PMID 32461349, 2020). "XCL1 expression was also significantly associated with the number of tumor-infiltrating CD8-positive T cells and PD-L1 expression on tumor cells." (PMID 32115573, 2020). "A ~3 x increase in XCL1 concentration was detected in tumor extracts from hetIL-15 treated mice compared with tumors from PBS treated mice." (PMID 32461349, 2020). "Taken together, these data indicate that hetIL-15 treatment promotes the production of the chemokine XCL1 by intratumoral lymphocytes leading to increased tumor infiltration by CD103+XCR1+IRF8+ cDC1." (PMID 32461349, 2020). "XCL1 expression in tumor cells was detected in 13 out of 24 MCT-SCC/ASCs (54%) and 1 out of 19 HGSCs (5.3%)." (PMID 32115573, 2020). "In MCT-SCC, we found XCL1 expression on tumor cells as well as some intratumor immune cells in XCL1-positive MCT-SCCs/ASCs." (PMID 32115573, 2020). "We also identified two new subsets, including CCL18+ M2 macrophages enriched in advanced HCC, and XCL1+ CD8+ T cells capable of recruiting DC to enhance anti-tumor response." (PMID 33298893, 2020). "A vaccine strategy based on XCL1- and IL-2-secreting neuroblastoma cells enhanced T-cell infiltration and resulted in complete or partial tumor remission in vaccinated patients." (PMID 30979057, 2019). "Recently, NK cell-derived XCL1 has been shown to recruit conventional type 1 DCs to the tumor microenvironment, which is critical to the antitumor immunity." (PMID 31477722, 2019). "During the same year, another study has targeted Xcr1+CD103+ DCs via laser-assisted intradermal ear vaccination with Xcl1-OVA fusion protein on day 3 post tumor graft." (PMID 30863405, 2019). "As in the previous experiment involving OT-1 T cell transfer, mice vaccinated with Xcl1-(OVA SLP)-Fc fusion protein showed better control of B16.OVA tumor growth, compared to other cohorts." (PMID 30863405, 2019). "Tumor NK cells produce chemokines XCL1 and CCL5 that bind to receptors expressed by cDC1 driving their accumulation in tumors." (PMID 30979057, 2019). "The recruitment of cDC1s to murine tumours was shown to depend on other NK cell-derived chemoattractants, specifically XCL1 and CCL5." (PMID 31091774, 2019). "One group inserted XCL1 and soluble Flt3L into a Semliki Forest Virus vector, which was then injected intratumourally, resulting in delayed tumour growth of MC38 and B16-OVA murine tumours." (PMID 31091774, 2019). "A screen of chemokine-transduced tumors identified CCL19, CCL22 and XCL1 as potent mediators of immune-based tumor rejection in vivo." (PMID 30979057, 2019). "We now further demonstrate the vaccine potency of Xcl1-antigen fusion proteins when injected on day 7 post-tumor graft, when EG7 tumors or the more aggressive B16.OVA tumors are fully established." (PMID 30863405, 2019).
tumor (continued). "Here, we uncover a key role for NK cells in the production of chemoattractants, including CCL5 and XCL1/2, that are necessary for the accumulation of cDC1 in incipient tumors and for tumor immune control." (PMID 29429633, 2018). "We conclude that cDC1 accumulation within the TME can be induced by the cDC1-recruiting chemokines CCL5 and XCL1 to improve tumor immune control." (PMID 29429633, 2018). "Because XCL1, the ligand for the chemokine receptor XCR1 expressed by cDC1, was not represented in the protein or the cytometric bead arrays, we analyzed tumor extracts for Xcl1 mRNA." (PMID 29429633, 2018). "Assessing the chemokine expression profile of tumor-residing immune cell subsets, the authors showed that XCL1 is produced exclusively by NK cells while CCL5 is secreted by both NK cells and CD8+ effector T cells." (PMID 29986768, 2018). "The XCL1/gp100-DC immunized mice exhibited resistance to tumor challenge more effectively compared to controls." (PMID 24967094, 2013). "The fusion of Xcl1 also increased immune cell infiltration into the tumor microenvironment." (PMID 39852828, 2025). "Notably, recent studies suggest that NK cell‐derived XCL1 plays a crucial role in recruiting dendritic cells to the tumour microenvironment, which is critical for antitumour immunity." (PMID 41405449, 2025). "Our findings proposed that XCL1 may play a key role in anti-tumor immunity and XCL1+ CD8+ T cell population could be a potential target to improve responses for immunotherapy in HCC." (PMID 41426973, 2025). "NK cell-derived XCL1 has been strongly implicated in the direct recruitment and activation of Clec9a+XCR1+ cDC1s into solid tumors, with cDC1s being essential for tumor antigen cross-presentation in tumor-draining lymph nodes." (PMID 40410571, 2025). "In order to understand the reasons why the fusion chemokine Xcl1 enhances the anti-tumor activity driven by the E6E7 antigen, we conducted a detailed analysis of specific immune and innate immune cell subpopulations within tumors of mice following vaccine administration." (PMID 39852828, 2025). "Similarly, peptide vaccination of OVA synthetic long peptide (SLP) fused with XCL1 led to greater tumor control of B16-OVA melanoma tumors with higher CD8 T cell tumor infiltration." (PMID 38903502, 2024). "Characterisation of tumour cells expressing NK marker genes, especially XCL1, is essential to uncover molecular mechanisms and pathways which may offer alternative therapeutic targets and candidate drugs for this subgroup of ESCC." (PMID 39419971, 2024). "All these observations suggest that XCL1 expressed by tumour or dysplastic cells may have a tumour-promoting role in ESCC." (PMID 39419971, 2024). "However, in our samples, the XCL1-overexpressing tumours showed the lowest immune cell infiltration." (PMID 39419971, 2024). "XCL1 can recruit conventional type I dendritic cells (cDC1) to colonize the tumor tissue." (PMID 37251333, 2023). "Additionally, NK cell-derived chemokines including CCL5 and XCL1 can also mediated recruitment of DCs into the tumor leading to improved tumor control in murine solid tumor models." (PMID 38022679, 2023). "Among 28 chemokine genes available, CXCL9/10/11/CXCR3, CXCL13/CXCR5 and XCL1/XCR1 mRNA expression were significantly increased in RCC compared to normal kidney tissue and also strongly associated with tumor-infiltrating effector memory and central memory CD8+ T cells in all investigated collectives." (PMID 37006314, 2023). "Moreover, CCL5 and XCL1 produced by tumor-infiltrating NK cells and innate lymphoid cells promoted the recruitment and activation of XCR1+ cDC1s, fostering NK-cDC1 axis-related control of tumor growth." (PMID 36949244, 2023). "In addition, C2 overexpressed the dimNK-related marker FCGR3A, while C1 overexpressed the briNK-related marker XCL1 which has been shown to recruit conventional type 1 DCs to the tumour microenvironment." (PMID 36855107, 2023).
tumor (continued). "CCL3, CCL19, CCL21, and XCL1 exhibited potent anti-tumor activities in vivo, although they might differentially regulate immune cells in the TME and antigen transfer to lymph nodes." (PMID 36654820, 2022). "Conversely, expression of XCL1, which when produced by tumor cells may induce PD1/PD‐L1 interaction and dysfunction of CD8+ T cells in the tumor microenvironment, was higher in CDKN2A/BHDIFN‐IHD tumors than in CDKN2A/BHDIFN‐IWT tumors." (PMID 35253368, 2022). "Complementing the hypothesis that cDC1s migrate in the tumor through the XCL1/2 – XCR1 axis, we show that, besides for NK-cells, XCL1/XCL2 were also expressed by a subpopulation of ENTPD1+ ITGAE+ CD8+ T-cells." (PMID 36741389, 2022). "XCL1 forms a connection with tumor suppressors: IRF8 and ITK in early cancer stages." (PMID 35610556, 2022). "This strategy could be extended beyond the model epitope S7Abu, as demonstrated by generation of XCL1-antigen conjugates with epitopes of tumor antigens gp100 (Y7A), TGFβRII (R7A) and caspase 5 (F7M)." (PMID 35428705, 2022). "Additionally, NK cells directly attract cDC1 accumulation inside the tumor lesion by XCL1 and CCL5 chemokines and promote their differentiation under the release of Flt3 factor with a strong inhibition of this axis induced by PGE2 tumor secretion." (PMID 36230990, 2022). "The increased tumor antigen ZsGreen in the lymph nodes of XCL1-overexpressing tumor models may be partially attributed to the increased antigen uptake in the tumor." (PMID 36654820, 2022). "Furthermore, our findings also revealed an unexpected role of XCL1 in enhancing tumor antigen uptake by cDCs and antigen transfer to lymph nodes." (PMID 36654820, 2022). "In addition, the immunomodulatory effects of LGG also promoted tumor regression by increasing the expression of lymphotactin (XCL1) to recruit T and NK cells." (PMID 36140470, 2022). "In addition, natural killer (NK) cells are also known to secrete XCL1 and have been shown to interact with cDC1s in the tumor microenvironment." (PMID 34065346, 2021). "In addition, the intratumor inoculation of XCL1 increased cDC1 accumulation and improved tumor control in several preclinical models." (PMID 32486257, 2020). "Interestingly, one of the immune checkpoints, PD-L1, was found to be expressed on MCT-SCC tumor cells and was correlated with X-C motif chemokine ligand 1 (XCL1) expression and intratumor infiltration of CD8-positve T cells." (PMID 32611433, 2020). "In addition, PGE2 inhibits XCL1 and CCL5 secretion by NK cells, underlining the role of PGE2 as an immunosuppressive mediator to interfere with cDC1s migration to the tumor." (PMID 33679726, 2020). "While chemokines, such as CCL5, may also recruit cells that promote tumor growth, such as Treg and macrophages, XCL1 is a specific chemoattractant for cDC1s and this chemokine could be exploited in cDC1-targeted therapies." (PMID 32486257, 2020). "However, both groups of mice showed fast tumor growth, confirming the adjuvant effect of Xcl1 fusion proteins." (PMID 30863405, 2019). "Tumor-associated CD8+ T cells expressing exhaustion markers across all four tumor types project onto activated CD8+ T cells in our map, and express genes within the Cytokine module (CCL3, CCL4, XCL1, XCL2, and IFNG), and to a lesser extent Cytotoxic module." (PMID 31624246, 2019). "In this context, it will be important to evaluate if tumor control could be further enhanced by combining Xcl1-SLP-Fc vaccination with immune checkpoint blockade, as demonstrated by us and others in pre-clinical and clinical settings." (PMID 30863405, 2019). "Other cells such as CD8+ T cells and innate lymphocytes [e.g., γδ T cells, innate lymphoid cells (ILC1s)] are in principle able to produce both CCL5 and XCL1 and might contribute to cDC1 recruitment under certain circumstances or in other tumor contexts." (PMID 30352680, 2018).